MFSD6 (major facilitator superfamily domain containing 6)
Description:
(Microbial infection) Acts as a receptor for respiratory enterovirus D68. Mechanistically, binds to viral particles and is required for viral cell entry while initial attachment to cells is mainly mediated by interactions with sialic acid.
Synonyms: MMR2; SLC73A1; FLJ20160; hMMR2
Tractability: Antibody: UniProt predicts a signal peptide or a membrane-spanning region; its Gene Ontology location is reachable by antibodies, with medium confidence. PROTAC: ubiquitination databases record sites on it; its protein half-life has been measured.
Gene: Protein-coding gene on chromosome 2 (190,408,355 to 190,509,205, forward strand). Ensembl gene ENSG00000151690.
Subcellular location: Cell membrane
Subcellular location (Human Protein Atlas): Cytosol; Nucleoplasm
Gene Ontology:
Molecular function: protein binding; MHC class I protein binding; MHC class I receptor activity
Biological process: antigen processing and presentation of exogenous peptide antigen via MHC class I
Cellular component: membrane; plasma membrane
Genetic constraint (gnomAD): Loss-of-function variants: 25 observed, 57.2 expected, observed/expected ratio (o/e) 0.44, 90% interval 0.32 to 0.61. The upper end of that interval is the gene's LOEUF score, 0.61, which puts it in group 2 of 6, group 1 being the genes least tolerant of losing a copy. Missense variants: 744 observed, 1,017.3 expected, observed/expected ratio (o/e) 0.73, 90% interval 0.69 to 0.78. Synonymous variants: 330 observed, 380.63 expected, observed/expected ratio (o/e) 0.87, 90% interval 0.79 to 0.95.
Homologues: Orthologues: chimpanzee MFSD6 (99% identical), macaque MFSD6 (98% identical), mouse Mfsd6 (88% identical), rat Mfsd6 (88% identical), dog MFSD6 (88% identical), guinea pig MFSD6 (87% identical), pig MFSD6 (84% identical), rabbit MFSD6 (82% identical), tropical clawed frog mfsd6 (64% identical), zebrafish mfsd6a (55% identical), zebrafish mfsd6b (47% identical), Drosophila melanogaster jef (31% identical), and 1 more. Paralogues in human: MFSD6L (15% identical).
Diseases named in the same sentence as MFSD6 in open-access papers:
MFSD6 is named in the same sentence as 10 diseases in open-access papers, as found by Europe PMC text mining. Sharing a sentence is not in itself a finding about the gene and the disease. The quoted sentences say what the papers report.
ovarian carcinoma (2 papers, 2018 to 2025). A malignant neoplasm originating from the surface ovarian epithelium. "To estimate the clinical relevance of DGKH, FBXL7, and MFSD6 in patients with ovarian cancer, we next performed Kaplan-Meier analysis using the K-M Plotter database." (PMID 30301218, 2018). "Under the condition of progression-free survival (PFS) probability, we found that FBXL7 and MFSD6 transcripts at high levels—but DGKH at low levels—significantly (p < 0.05) predicted a poor prognosis in the unclassified ovarian cancer patients." (PMID 30301218, 2018). "In addition, Kaplan-Meier analysis for other DGKH and MFSD6 microarray probes using the K-M Plotter database against the unclassified ovarian cancer patients yielded similar results under the condition of PFS probability." (PMID 30301218, 2018). "In the ovarian cancer patients with taxol adjuvant therapy, the other DGKH, except probes 227415_at and 1553300_a_at, and MFSD6 microarray probes displayed similar prognostic significance under PFS probability." (PMID 30301218, 2018). "Similarly, in the ovarian cancer patients receiving taxol adjuvant therapy, the elevated mRNA levels detected by probes for DGKH (except probes 235952_at and 240145_at), FBXL7, and MFSD6 appeared to be correlated with poor outcomes." (PMID 30301218, 2018).
sarcoidosis (2 papers, 2020 to 2022). Sarcoidosis is a multisystemic disorder of unknown cause characterized by the formation of immune granulomas in involved organs. "Because sarcoidosis is a granulomatous disease, we found autoAbs against macrophage-associated antigens, including major facilitator superfamily domain containing 6 (MFSD6) and myocyte enhancer factor 2D (MEF2D) in our analysis of serum autoAbs from patients with a definite diagnosis of sarcoidosis." (PMID 32046322, 2020).
Hepatic fibrosis (1 paper, 2025). The presence of excessive fibrous connective tissue in the liver. "Additionally, MFSD6 and ANXA4 were positively correlated with ALP, ALT, and hepatic fibrosis, indicating their roles in liver function." (PMID 41245305, 2025).
psoriasis (1 paper, 2024). An autoimmune condition characterized by red, well-delineated plaques with silvery scales that are usually on the extensor surfaces and scalp. "Then, the expression of top 5 potential candidate genes (PBX1, CYB5R4, SAR1A, CXCR5, MFSD6) of miR-3074-5p was detected in normal and psoriasis tissues by qPCR; our result revealed that PBX1 was the most upregulated genes in psoriasis tissues compare to normal ones." (PMID 38240925, 2024).
MFSD6 also shares sentences with these, for which no sentence is quoted: tumor (3 papers); infection (2); cancer (1); endometriosis (1); Lynch syndrome (1); mumps (1).